TWIST1 (twist family bHLH transcription factor 1)
Diseases named in the same sentence as TWIST1 in open-access papers (continued):
Sharing a sentence is not in itself a finding about the gene and the disease.
breast carcinoma (continued). "The NetPert method and two alternative methods, betweenness centrality (BC) and TieDIE, were applied to the Twist1-driver mouse model of epithelial cell dissemination in breast cancer with 182 significantly differentially expressed genes." (PMID 38935814, 2024). "In breast cancer, epithelial-mesenchymal transition (EMT) is positively associated with programmed death ligand 1 (PD-L1) expression and immune escape, and TWIST1 silences ERα expression and induces EMT and cancer metastasis." (PMID 38893094, 2024). "Accordingly, knockdown of TWIST1 or BRD8 or inhibition of PD-L1 significantly enhances the tumor antigen-specific CD8+ T cells to suppress the growth of breast cancer cells." (PMID 38893094, 2024). "At present, the expression of Twist1 is abnormally high expression in many tumors, such as breast cancer, prostate cancer, hepatocellular carcinoma." (PMID 38191892, 2024). "The treatment of estrogen-responsive breast cancer cell lines with doxorubicin strongly stimulates TWIST1 expression, consequently raising miR-10b levels." (PMID 38473317, 2024). "The MCF7-Ctrl and MCF7-TWIST1 cells used in this study represent a progression model from ER+/HER2− to ER−/HER2− breast cancer cells reprogrammed by TWIST1-induced EMT." (PMID 38893094, 2024). "TWIST1 expression is positively correlated with CD274/PD-L1 expression in metastatic breast cancers and TNBC cell lines." (PMID 38893094, 2024). "Collectively, these results indicate that breast cancer cells with a TWIST1-promoted high expression of PD-1 significantly accelerate CD8+ cytotoxic T-cell exhaustion and death." (PMID 38893094, 2024). "These novel observations clearly demonstrate that TWIST1 strongly upregulates PD-L1 expression in ER−/HER2−/TWIST1+ breast cancer cells in addition to inducing EMT to promote breast cancer invasion and metastasis." (PMID 38893094, 2024). "NF-κB increases EMT-associated genes SNAI1, TWIST1, ZEB1, and VIM in a variety of disease processes including pulmonary lung fibrosis and many cancers: head and neck, prostate, pancreatic, and breast cancer." (PMID 39348939, 2024). "This study analyzed TWIST1 and PD-L1 expression in breast cancers, investigated the mechanism for TWIST1 to regulate PD-L1 transcription, and assessed the effects of TWIST1 and PD-L1 in cancer cells on cytotoxic CD8+ T cells." (PMID 38893094, 2024). "The TieDIE method was applied to the IID and TRRUST network to prioritize all genes for the Twist1 driver mouse model of epithelial cell dissemination in breast cancer with 182 differentially expressed genes." (PMID 38935814, 2024). "They concluded that TWIST1 upregulation is a potential target for reversing resistance to the CDK4/6 inhibitor in metastatic luminal breast cancer cells." (PMID 38540112, 2024). "The TWIST1-upregulated PD-L1 in breast cancer cells drives immune evasion in vitro by suppressing the cancer cell-killing activity and causing the exhaustion and death of CD8+ T cells." (PMID 38893094, 2024). "We are aware of the limitations of these experiments, including the usage of only two independent parent cell lines and the requirement of more cell lines, especially more TNBC cell lines, to generalize this regulatory axis to all TWIST1+ breast cancer cells." (PMID 38893094, 2024). "In this study, we demonstrated that TWIST1-upregulated PD-L1 in breast cancer cells significantly suppresses the cancer cell-killing activity of CD8+ T cells and accelerates their exhaustion and death in the coculture." (PMID 38893094, 2024). "At present, the expression of Twist1 is abnormally high in many tumors, such as breast cancer, prostate cancer and hepatocellular carcinoma." (PMID 38191892, 2024). "Conversely, the knockdown of TWIST1 in ER−/HER2− breast cancer cells such as BT549 and 4T1 cells with endogenous TWIST1 expression significantly inhibited their invasion and metastasis capabilities." (PMID 38893094, 2024).
breast carcinoma (continued). "SRC‐1 upregulates the expression of ERBB2, colony‐stimulating factor 1 and TWIST1 thereby promoting metastasis in breast cancer." (PMID 38506084, 2024). "MicroRNA-34a is considered another inhibitor of the EMT, and it has been described that its protective effect against breast cancer invasion and metastasis is accomplished by the inhibition of TWIST1." (PMID 38473317, 2024). "The NetPert, BC, and TieDIE methods were applied to each network to rank all genes for the Twist1-driver mouse model of epithelial cell dissemination in breast cancer." (PMID 38935814, 2024). "Increased expression of TWIST1 has been observed in various types of tumor cells, including prostate, gastric, and breast cancer." (PMID 37511550, 2023). "FBXO3 can bind to and stabilize USP4, leading to Twist1 protein stabilization and increased breast cancer cell migration and tumor metastasis." (PMID 38134227, 2023). "We found that the effect of USP13 in promoting the migration and invasion capacities of breast cancer cells can at least partly be achieved through its regulation of Twist1, while Twist1 can inhibit the transcriptional activity of USP13." (PMID 36732432, 2023). "Clinically, elevated expression of p110α/FBXO3/USP4/Twist1 is associated with poor overall survival (OS) and recurrence-free survival (RFS) of breast cancer patients." (PMID 38134227, 2023). "Harmine was also used to inhibit TWIST1 in luminal breast cancers, where it was able to resensitize palbociclib-resistant MCF7 cells to CDK4/6 inhibitors." (PMID 38139368, 2023). "Immunohistochemical analyses of human breast tissue microarray (TMA) showed a significant positive correlation of the expression of FBXO3 and Twist1 in breast cancer samples (p < 0.0001)." (PMID 38134227, 2023). "When these MSCs were co-cultured with a breast cancer cell model, there was a coincident reduction in EMT-associated genes (e.g., ZEB1/2, TWIST1, SNAIL, FOXC2, N-Cadherin)." (PMID 36940196, 2023). "In breast cancer, silencing of FOXA1 expression by Twist1 is the main cause of Twist1-induced migration, invasion, and metastasis." (PMID 36998469, 2023). "Studies also found that TWIST1 decreases the transcription of E-cadherin and α, β, and γ-catenins in breast cancer cells." (PMID 38139368, 2023). "Increasing stiffness of the surrounding ECM has been shown to induce EMT in breast cancer cells by promoting TWIST1 to translocate into the nucleus." (PMID 36940196, 2023). "First, USP29 and TWIST1 protein levels were examined in several luminal and basal like breast cancer cell lines." (PMID 36782089, 2023). "Scratch wound healing, cell migration and invasion assays, and a mouse lung metastases assay were used to investigate the roles of USP13 and Twist1 in promoting breast cancer metastasis." (PMID 36732432, 2023). "Up-regulation of TWIST1 protein expression in breast cancer cells can promote EMT, stem cell phenotypes, and tumorigenicity, whereas down-regulation can inhibit the EMT process without affecting growth at the primary tumor site." (PMID 37115802, 2023). "Among these 4 upstream TFs, PRRX2, TWIST1, and PRRX1 were reported to induce mesenchymal–epithelial cell transformation and were associated with breast cancer metastasis." (PMID 37736108, 2023). "Knockout or downregulation of the transcription factor gene FOXA1 has also been linked to worse prognosis, altering the carcinogenic activity of the Snail/Twist1 axis in breast cancer as well as prostate cancer." (PMID 37895248, 2023). "Rising ECM stiffness fostered invasion and migration of breast cancer cells through translocating TWIST1 into nuclear, thereby promoting cellular transcriptional activity." (PMID 36698043, 2023). "PRRX1 cooperates with Twist1 to induce EMT during embryogenesis and tumor invasion, but overexpression of PRRX1 is associated with a favorable prognosis in breast cancer patients." (PMID 35601657, 2022).
breast carcinoma (continued). "The 4T1 family of isogenic mammary tumors has been used by several researchers to identify important genes that drive breast cancer metastasis such as TWIST1, FOXC2, and CXCR3 39-41." (PMID 35910801, 2022). "For example, during breast cancer metastasis, Twist1 interacts with SET8 thus inducing a H4K20 monomethylation mark at the promoter of E‐cadherin and N‐cadherin, which downregulates and upregulates the transcription, respectively." (PMID 35601657, 2022). "To substantiate the correlation of SPOP and TWIST1 protein levels, we collected invasive ductal carcinoma tissues from Chinese breast cancer patients and adjacent normal tissues for analysis." (PMID 36115849, 2022). "The TWIST1/Mi2/NuRD protein complex is inhibited by E-cadherin expression to promote EMT to induce breast cancer metastasis, demonstrating that knockdown of TWIST1 plays an essential role in the inhibition of metastatic breast cancer." (PMID 35743249, 2022). "The inverse correlation between SPOP and TWIST1 in breast carcinoma tissues and their functional interplay prompted us to address the regulatory mechanisms." (PMID 36115849, 2022). "Clinically, SPOP is negatively correlated with the levels of TWIST1 in highly invasive breast carcinomas." (PMID 36115849, 2022). "Taken together, we have linked SPOP to TWIST1 destabilization for its tumor suppressive functions such as inhibiting EMT and metastasis of breast cancer cells." (PMID 36115849, 2022). "This event contributes to the Twist1‐induced metastasis of breast cancer, but less responsible for Twist1‐induced EMT phenotype of breast cancer cells, which is interesting." (PMID 35601657, 2022). "Our and other previous studies have revealed important roles and mechanisms of TWIST1 in breast cancer metastasis." (PMID 36115849, 2022). "In this study, we elucidate a tumor-suppressive role of SPOP in advanced breast cancer by negatively controlling TWIST1 stability." (PMID 36115849, 2022). "A knockout of TWIST1 in breast cancer cells inhibited the expression of EMT markers and prevented metastases in immune-deficient mice." (PMID 35465155, 2022). "Altered expression of TWIST1 has also been implied in the development of different cancers, including breast cancer." (PMID 36115849, 2022). "TWIST1 is upregulated in several cancers, including glioma, sarcoma, melanoma, and carcinomas of the breast and the squamous tissue." (PMID 36474162, 2022). "In the aggregate, these results suggest that the outcomes of SPOP on breast cancer malignancy are mediated, at least in part, by TWIST1." (PMID 36115849, 2022). "The role of Twist1 has already been shown to serve as a useful prognostic factor predicting poor outcome in breast cancer, nasopharyngeal cancer, ovarian cancer and cervical cancer." (PMID 34234737, 2021). "Overexpression of miR-580 inhibited cell motility in breast cancer by downregulating TWIST1, implying that miR-580 functioned as a tumor suppressor." (PMID 34516354, 2021). "TWIST1 directly represses CD24 expression through the E-box element to increase the CD44+/CD24−/low cancer stem–like cell population in breast cancer cells." (PMID 34809669, 2021). "Twist1 is overexpressed in aggressive breast cancers and is also known to promote breast cancer metastasis to the bone." (PMID 33414456, 2021). "Overexpression of TWIST1 in breast cancer cell lines were shown to promote the ability of mammosphere to self-renew in vitro as well as promote tumor initiation ability in immunodeficient mice." (PMID 34277708, 2021). "We previously revealed that Twist1 was overexpressed in breast cancers with higher node status and clinical stage and positively associated with EMT in breast cancer." (PMID 34249678, 2021).
breast carcinoma (continued). "For example, TWIST1 was found to promote metastasis in the breast cancer model but was shown to be dispensable for metastasis in a pancreatic cancer model." (PMID 34948036, 2021). "TWIST1 expression level is higher in the doxorubicin-resistant samples than the doxorubicin-sensitive samples collected from breast cancer patients." (PMID 33768509, 2021). "Phosphorylation at Ser68 of Twist1 by MAPK has been reported to increase Twist1 stability in breast cancer cells." (PMID 33808323, 2021). "Recently, it has also been demonstrated that, in a bone-seeking sub-population of metastatic breast cancer cells, TWIST1 promotes bone metastasis formation." (PMID 33830428, 2021). "Another in vivo model of breast cancer, based on Twist1 overexpression in the context of H-Ras activation, led to a highly undifferentiated tumor with EMT features and claudin-low phenotype." (PMID 34768901, 2021). "TQ induced the methylation of the Twist1 promoter in the breast cancer cell line, which led to the downregulation of Twist1." (PMID 33923474, 2021). "In conclusion, our study shows that harmine induces Twist1 degradation in a dose dependent manner in breast cancer cells and inhibits their migration and invasion." (PMID 33626096, 2021). "In accordance, TWIST1 KO in breast cancer cells inhibits the expression of epithelial to mesenchymal transition (EMT) markers, preventing metastases formation in immune-deficient mice." (PMID 33983406, 2021). "A positive correlation between the AEG-1 and TWIST1 levels was observed in breast cancer clinical samples." (PMID 33918653, 2021). "Twist1-overexpressing breast cancer cells up-regulated Akt2 transcription, which promotes resistance to paclitaxel." (PMID 33768509, 2021). "Twist1 is overexpressed in a variety of cancers and is a well-documented master regulator of breast cancer metastasis." (PMID 33626096, 2021). "Known targets of miR-720 include TWIST1 in breast cancer, Rab35 in cervical cancer, StarD13 in colorectal cancer, and CCND1 in pancreatic cancer." (PMID 33880375, 2021). "The Twist1-positive rate was significantly higher in ER- (113/147; 76.9%) than in ER+ (107/261; 41.0%) breast cancer (P < 0.001)." (PMID 34249678, 2021). "Overexpression of Twist1 is common in metastatic carcinomas including in aggressive and metastatic forms of breast cancer." (PMID 33626096, 2021). "IL-1β induces tamoxifen resistance in the breast cancer cell model via prompting of Twist1 that propels methylation in the promoter region of the ESR1 gene which in turn reduces the expression of Erα." (PMID 34220337, 2021). "As a master regulator of EMT in breast epithelial cells, Twist1 is a promising target for metastatic breast cancer therapy." (PMID 33626096, 2021). "The expression level of Snail, Sox4, and Twist1 was significantly decreased in miR-381-3p-overexpressed breast cancer cells." (PMID 34362391, 2021). "LncRNA activated by transforming growth factor-b (ATB) contributes to Twist1 expression and breast cancer epithelial–mesenchymal transition (EMT) through inhibiting miR-200c." (PMID 32156248, 2021). "In early stages of breast cancer metastasis progression, miR-10b promoted by TWIST1 inhibits the expression of the transcription factor homeobox D10, thus leading to the over-expression of a pro-metastatic factor, RHOC, in cancer cells." (PMID 33830428, 2021).
breast carcinoma (continued). "Twist1 is also suggested to be a useful biomarker for predicting resistance to doxorubicin, used widely for adjuvant chemotherapy of breast cancer." (PMID 33768509, 2021). "Since TWIST1 has been reported to be involved in progression of breast cancer, the effect of TFPI2 on TWIST1 expression was determined in breast cancer." (PMID 32248791, 2020). "ERK1 and ERK2, together with other MAPKs JNK and p38 MAPK, were found to stabilize the phosphorylation site of TWIST1 for EMT induction in breast cancer cells." (PMID 32322559, 2020). "Together, these findings provide clear evidence that AUF1 is an important inducer of the EMT process through stabilization of SNAIL1 and TWIST1 and the consequent promotion of breast cancer stem cells." (PMID 32759946, 2020). "Down-regulation of luminal breast cancer marker (Foxa1) and up-regulation of basal-like breast cancer markers (integrin α5 and integrin β1) were regulated by TWIST1 to promote breast cancer progression." (PMID 32248791, 2020). "Up-regulation of TWIST1 with down-regulation of ER expression has been uncovered in breast cancer, which is another common malignancy in women and is also estrogen-related." (PMID 33235117, 2020). "Signaling pathways involved in EMT transition, such as Wnt, participated in regulation of TWIST1 on breast cancer." (PMID 32248791, 2020). "Our results showed that TFPI2-mediated down-regulation of TWIST1 decreased integrin α5 thereby inhibiting breast cancer progression." (PMID 32248791, 2020). "In line with these, we wanted to contribute to the significance of Akt-mediated phosphorylation of TWIST1 by using mouse breast cancer cell model." (PMID 32922123, 2020). "The downstream signaling pathway involved in TFPI2/TWIST1/integrin α5 axis in breast cancer progression should also be investigated in the future study." (PMID 32248791, 2020). "Since TWIST1 expression is limited to specific organs in adults, it is conceivable that TWIST1 would be a cancer-preferential drug target to prevent metastasis of breast cancer." (PMID 32922123, 2020). "Spectral karyotyping (SKY) analyses of metaphases derived from Twist1 overexpressing MCF-7 (breast cancer cell line) showed an increase in chromosomal aberrations such as aneuploidy and translocations." (PMID 32337580, 2020). "The knockdown of asparagine in an in vivo breast cancer model induces the alteration of Twist Family BHLH Transcription Factor 1 (Twist1) and E-cadherin expression only at the metastasis site, which indicates an impaired EMT behavior." (PMID 32793478, 2020). "Our work is consistent with a prior report that Twist1 transcriptionally induces Ccl2 in breast cancer cell lines that leads to macrophage recruitment." (PMID 31933479, 2020). "Functional assays indicated that the inhibition abilities of TFPI2 over-expression on breast cancer progression were reversed by TWIST1 over-expression." (PMID 32248791, 2020). "TFPI2 inhibited TWIST1 expression to down-regulate integrin α5, and TFPI2/TWIST1/integrin α5 axis contributed to suppression of breast cancer progression, suggesting a novel insight into the treatment of the disease." (PMID 32248791, 2020). "Benezra and colleagues showed that during metastatic colonization, inhibitor of differentiation 1 (Id1), enhances breast cancer cells' stem-like phenotype by suppressing Twist1 and inducing an MET." (PMID 32391382, 2020). "Twist1 is known as a major transcription factor which can promote cell motility, migration, and invasion in breast cancer cells." (PMID 30819235, 2019). "HMGA2, SALL4, and Twist1 are overexpressed in breast cancer, facilitating the self-renewal of CSCs, and enlarging the population of CSCs, leading to the tumor acquiring a higher invasive and metastatic ability." (PMID 31861404, 2019).